ZNF826P (zinc finger protein 826, pseudogene)
Description:
May be involved in transcriptional regulation.
Synonyms: FLJ44894; formerly ZNF826
Gene: Transcribed unprocessed pseudogene on chromosome 19 (20,397,334 to 20,409,959, reverse strand). Ensembl gene ENSG00000231205.
Subcellular location: Nucleus
Diseases named in the same sentence as ZNF826P in open-access papers:
ZNF826P is named in the same sentence as 1 disease in open-access papers, as found by Europe PMC text mining. Sharing a sentence is not in itself a finding about the gene and the disease.
ZNF826P shares sentences with these, for which no sentence is quoted: lung carcinoma (1 paper).